FMR1-IT1 (FMR1 intronic transcript 1)
Gene: Long non-coding RNA gene on chromosome X (147,946,941 to 147,947,583, forward strand). Ensembl gene ENSG00000236337.
Diseases named in the same sentence as FMR1-IT1 in open-access papers:
FMR1-IT1 is named in the same sentence as 3 diseases in open-access papers, as found by Europe PMC text mining. Sharing a sentence is not in itself a finding about the gene and the disease.
FMR1-IT1 shares sentences with these, for which no sentence is quoted: breast carcinoma (1 paper); melanoma (1); tumor (1).